MIR511 (microRNA 511)
Synonyms: hsa-mir-511-1; hsa-mir-511-2; MIR511-1; MIR511-2; MIRN511-1; MIRN511-2; hsa-mir-511; mir-511
Gene: MicroRNA gene on chromosome 10 (17,845,107 to 17,845,193, forward strand). Ensembl gene ENSG00000207938.
Gene Ontology:
Biological process: miRNA-mediated post-transcriptional gene silencing